RAC1 (Rac family small GTPase 1)
Diseases named in the same sentence as RAC1 in open-access papers (continued):
Sharing a sentence is not in itself a finding about the gene and the disease.
cancer (continued). "In addition to the well-studied Rac1, we also report the importance of Rac2 and Rac3 in the regulation of cancer stemloids." (PMID 28160553, 2017). "Rac1 activity has been shown to be important to survival of cancer cells." (PMID 28410221, 2017). "However, given the contrasting roles of Rac1 in cancer, a thorough understanding of factors that influence Rac1 downstream specificity and biological output is needed prior to targeting Rac1 in a clinical setting." (PMID 27442895, 2017). "Thus, inhibition of Rac1 activity is a viable therapeutic strategy for proliferative disorders such as cancer." (PMID 28410221, 2017). "The mechanistic basis for the observed difference could be attributed to the addiction of cancer cells to Rac1 signaling." (PMID 28410221, 2017). "Additionally, Rac1 facilitates cancer cell invasion via controlling the expression and release of matrix metalloproteinases (MMPs), which are required for ECM proteolytic degradation." (PMID 27442895, 2017). "Interestingly, NSC23766-mediated Rac1 inhibition has been shown to inhibit Rac1-driven pro-tumorigenic effects in a number of cancer models." (PMID 27442895, 2017). "In conclusion, we demonstrate a novel function of XIAP BIR domain in regulating cancer cell anchorage-independent growth ability through the upregulation of EGFR translation via the inhibition of miR-200a transcription through the Rac1/PP2A/MAPKK/MAPK/c-Jun axis." (PMID 28057023, 2017). "In addition to cancer, deregulation of Rac1 signaling has been shown to drive cardiovascular diseases." (PMID 27442895, 2017). "The protective role of Rac1 in cancer has also been demonstrated in vivo." (PMID 27442895, 2017). "Our data suggest a crosstalk of NMU signaling with several cancer-relevant pathways including the WNT receptor cascade resulting in an increased activation of the WNT/PCP effector RAC1 as an indicator for enhanced cancer cell motility and down-regulation of the canonical WNT target MYC among others." (PMID 28423716, 2017). "The inhibition of RAC1 by aspirin will attenuate these processes, which may provide an alternative explanation for the anti-inflammation and cancer effect of aspirin." (PMID 26989626, 2016). "Rac1 is also required for K-Ras-induced lung tumors in mice, and cooperates with APC loss in a mouse model of colorectal cancer, driving a stem-cell like signature in the developing cancer cells." (PMID 27104658, 2016). "Taken together these data demonstrate the ability of Tiam1 and P-Rex1, irrespective of upstream signalling, to induce cell morphological changes and actin cytoskeletal rearrangements that govern Rac1-driven anti- and pro-migratory phenotypes, respectively, in both normal and cancer cell lines." (PMID 26887924, 2016). "SYJN2 is a novel Rac1 effector that is required for the formation of lamellipodia and invadopodia, as well as for tumour cell migration and invasion which makes it a novel potential target for therapeutic intervention in malignant tumours." (PMID 26463353, 2016). "Therefore, inhibition of Rac1 specifically in cancer cells would be a strategy to retard metastasis." (PMID 27791203, 2016). "Accordingly, enhancement of cancer cell migration by EGF appears to be linked to both the activation of the PI3K/Akt/Rac1/calpain pathway and SOCE increase, which is dependent onSTIM1 phosphorylation upon activation of both Rac1 and Akt regulation." (PMID 27102434, 2016). "Thus, GLS2 inhibits Rac1 activity, which in turn inhibits migration, invasion and metastasis of cancer cells." (PMID 26751560, 2016). "Ubiquitylation of Rac1, RhoA and Cdc42 can be deregulated in cancer cell lines, a fact that could indicate a link between Rho GTPase protein ubiquitylation and cancer." (PMID 27104658, 2016). "RAC1 mRNA levels were induced by the interaction of cancer cells with platelets." (PMID 27074574, 2016). "Further work is now needed to explore whether targeting Rac1 could be a potential therapy for cancers that have lost GLS2." (PMID 26751560, 2016).
cancer (continued). "Along with canonical TGF-β signaling through Smad-dependent transcriptional regulation, Crk-dependent EMT though Rac1 and RhoA activation may play a role in cancer progression." (PMID 27027347, 2016). "Here, DHA-induced, miR-30c-5p-mediated down-regulation of Rac1 expression might be another novel mechanism by which DHA inhibits cancer cell proliferation, viability, and migration." (PMID 27613829, 2016). "PD-L1 is a suppressor of the immune system thus its upregulation may allow cancers to evade the host immune system and therefore oncogenic Rac1 P29S may promote the reduction of anti-tumor immune response." (PMID 27104658, 2016). "However, little is known regarding the effects of Tβ4 on Rap1/Rac1 activation and Rap1- or Rac1-mediated cancer cell migration." (PMID 25888632, 2015). "While NSC23766 and Rac1N17 incompletely inhibited tumor metastasis in vivo, and H/R-experienced cancer cell migration in vitro, more efficient attenuation of cancer cell migration was accomplished by simultaneous inactivation of Rap1 and Rac1 with Rap1N17 and Rac1N17, respectively." (PMID 25888632, 2015). "The mobility of Tβ4-overexpressing cells was 30% higher than that of controls, suggesting that cancer cell migration may be dependent on Tβ4-mediated activation of Rap1- and Rac1-GTPases." (PMID 25888632, 2015). "In other words, Tβ4 may act as a regulator of cancer cell migration and tumor metastasis by regulating the interaction between Rac1 and Rap1 activity." (PMID 25888632, 2015). "However, our data limit to explain a mechanism on inhibition of cancer cell migration via Rap1 and Tβ4 up-regulation by blocking Rac1." (PMID 25888632, 2015). "Although the importance of Rac1/Cdc42 activation is well documented in cancer aggressiveness, the clinical importance of GIT1 remains largely unknown." (PMID 26462147, 2015). "Cancer cell migration was also dependent on Tβ4-induced activation of Rap1 and Rac1." (PMID 25888632, 2015). "Twist1 has been shown to mediate cancer migration through triggering Rac1 activation." (PMID 25868853, 2015). "Cancer cell migration in Rac1 inhibitor-treated H/R-experienced cells may therefore be maintained by a compensatory increase in Tβ4-mediated Rap1 activity." (PMID 25888632, 2015). "Our and other studies didn’t show alteration of RhoGDI2 expression could results in Rac1 protein level change in cancer cells." (PMID 25901126, 2015). "This suggests that Tβ4 may act as a central mediator of Rap1 and Rac1 activation, and that together, Rap1 and Rac1 could be an efficient therapeutic target for the prevention of tumor metastasis and cancer cell migration." (PMID 25888632, 2015). "As Rac1 is frequently over-expressed or over-activated in cancers, we reasoned that lipin-1 might also be over-expressed in various cancer cell lines as compared to normal skin fibroblasts or endothelial cells." (PMID 25834103, 2015). "The development of drugs regulating the expression of Rac1, Rock1 and Pak1 may more accurately regulate actin activity which may be more beneficial in the prevention and treatment of diseases such as cancer." (PMID 23298303, 2014). "Cancer cells of IMPC may have abnormalities of RAC1 suppression cascade and show the characteristic ‘inside-out’ structures." (PMID 25109922, 2014). "In response to extracellular ligand binding, integrins undergo a conformational change that permits the recruitment of cytoplasmic adaptor proteins and signaling molecules, including small Rho GTPases, Cdc42, Rac1 and RhoA, which are key players in cell migration and cancer metastasis." (PMID 25149533, 2014). "However, the role of Hax-1 in cancer cell migration or its role in Rac1-cortactin complex formation, which is known to be required for such migration remains to be characterized." (PMID 25053987, 2014). "The cell-type specificity or developmental stage of cancer cells might explain the conflicting roles of Rac1 in cancer cells." (PMID 24523903, 2014).
cancer (continued). "Since Rac1 is a critical regulator of metastatic activities of cancer cells, it is logical to suggest that inhibition of Rac1 expression or activity could result in the repression of metastatic potential of carcinoma cells." (PMID 25594058, 2014). "However, most of literature addressing the role of Rac in cancer progression concern Rac1, with little mention of Rac3." (PMID 24684802, 2014). "This strategy may be beneficial not only in cancers where DGKζ is overexpressed, but possibly also in cases where DGKζ is expressed at normal levels but Rac1 or RhoA are overexpressed or hyperactive." (PMID 24646293, 2014). "However, there are conflicting reports regarding the role of Rac1 in maintaining cell junctions and the invasion of cancer cells." (PMID 24523903, 2014). "Rho GTPase Rac1 is closely related with cell invasion and metastasis of cancers." (PMID 25136657, 2014). "We next aimed to determine whether overexpression of Rac1 protein in treatment-resistant malignant tumors enriched in CSCs could contribute to metastatic spread via development of additional new blood vessels." (PMID 25594058, 2014). "Rac1 is important in regulating cell proliferation of some cancer cell lines." (PMID 24667766, 2014). "Therefore, it is possible to suggest that inhibiting Rac1 signaling in the detached carcinoma cells would combat anoikis resistance and thus result in cell death of the most treatment-resistant cells having increased metastatic activities, i.e. of the CSCs." (PMID 25594058, 2014). "Hence, it is possible to assume that Rac1 is involved in regulation of the metastatic abilities of carcinoma cells." (PMID 25594058, 2014). "Additionally, aberrant activation of upstream regulators of RAC1, particularly in the DBL family of guanine nucleotide exchange factors (GEF) specific for RAC1 (e.g., TIAM1, PREX1-2, and ECT2), has been implicated in various cancers." (PMID 24416617, 2013). "Furthermore, aberrant activation of upstream regulators of RAC1, particularly in the DBL family of GEFs specific for RAC1, has been implicated in various cancers." (PMID 24146998, 2013). "However, most of the literature addressing the role of Rac in cancer aggressivity concerns Rac1, and studies on the role of Rac3 in cancer progression are far less abundant." (PMID 23388133, 2013). "The role of Rac1 in cancer progression has also been clearly shown." (PMID 23388133, 2013). "Rac1 activation also played a critical role in the migration of cancer cells." (PMID 22454661, 2012). "We have also shown that activation of Rac1-Pak1/2 pathway is involved in oncogenic transformation of Rat-1a cells, implying that similar mechanism by 14-3-3ζ in cancer cells may enhance tumor growth, transendothelial migration and metastasis." (PMID 22808202, 2012). "Since AKT and Rac1 require each other for their activation, our findings suggest that loss of miR-204 expression in human tumors may induce the positive feedback loop between BDNF/AKT1/mTOR and Rac1 during cancer cell migration and invasion." (PMID 23285024, 2012). "Thus, it is likely that Rac1 knockdown effects tumor cell lung colonization, growth due to a combined effect on cancer cell homing and proliferation in the lung." (PMID 21347385, 2011). "Despite the level of interest in the association of Rac activity with mutant Ras in cancer, there is no data showing that Ras-driven tumors from either mouse or clinical studies are associated with elevated Rac1 activity." (PMID 21358804, 2011). "Our data suggested that Rac1 and its downstream effector Pak1 may be involved in the progression of this cancer." (PMID 20426825, 2010). "Rac1 could contribute to cancer cell proliferation via regulation of the cell cycle: for example, it stimulates expression of cyclin D1, and induces cell transformation in vitro." (PMID 20822528, 2010).
cancer (continued). "Pak1 is the best-characterized downstream effector of Rac1, but it is also an important convergence point for many signaling pathways (including small GTPases and several tyrosine kinases) that are often activated in cancer cells." (PMID 20426825, 2010). "It is possible that this relationship between Rac1-mediated increase in p66shc might lead to an increase in expression of Eps8, which eventually might lead to the development of cancer." (PMID 20565814, 2010). "Therefore, it is likely that Rac1 and Pak1 have a role in determining the local invasive and metastatic potential of various human cancers." (PMID 20426825, 2010). "Also, an increase of Rac1 activity and Pak1 expression in the primary tumor was correlated with poorly differentiated cancer, local invasion, lymph node metastasis, LVI, and an unfavorable prognosis." (PMID 20426825, 2010). "Mounting evidence strongly implicates the dysregulation of Rac1 in cancer development." (PMID 18826597, 2008). "Additionally, volcano plots of the differentially expressed genes in these cancers indicated that in the RAC1 low-expression group, the expression levels of B cell surface markers (such as CD19, CD79A, and MS4A1) and immunoglobulin-related genes (such as IGHG1 and CR2) were higher." (PMID 39898257, 2025). "Moreover, not only was RAC1 activity higher in the recurrence groups but also the proportion of biopsies positive for RAC1-GTP was considerably higher in the recurrence group than in the remission group for both cancer types." (PMID 40633540, 2025). "Thus, RAC1-A159V mutant cancers other than HNSCC may also be potentially druggable by RAC1 targeting, in principle." (PMID 39941730, 2025). "In addition, RAC1 has been found to phosphorylate AKT in various cancers." (PMID 38385857, 2024). "The study also suggests the modulation of Rac1-p66Shc signaling and scavenging of ROS by quercetin could be prime mechanisms through which dietary flavonoids exert their antioxidant effects, which may play a critical role in their protective action in cancers." (PMID 38362155, 2024). "Also the recent study publishedin Nature revealed that Rac1 could be a priority target for cancer therapy, with statistics to support its feasibility." (PMID 40162454, 2024). "Additionally, our data suggest that Rac1 inhibition could be an important strategy to overcome resistance to therapy in different cancer types." (PMID 39513883, 2024). "Finally, given the importance of maintaining a balance in RAC1 expression, transport, and signalling in cells, regulating epigenetic modifications of the RAC1 gene could be useful as a therapeutic approach in cancer and other disorders." (PMID 40396280, 2024). "Additionally, knockdown reduced levels of β-catenin and Rac1 proteins as well as downstream target genes, confirming the interaction of DDX3X with the Rac1/β-catenin pathway in cancer progression and indicating a potential therapeutic target for tumors with increased Wnt activity." (PMID 38539466, 2024). "The evidence that this gene co-amplification occurs in different human cancers could suggest a functional relationship between CBX3, EGFR and RAC1 genes which normally occurs in physiological conditions but that could promote cancer progression when dysregulated." (PMID 37633946, 2023). "Therefore, restraining Rac1 activation is the key to cancer therapy." (PMID 37049739, 2023). "Altogether, after receiving upstream signals from Rac1, the Scar/Wave complex regulates F-actin cytoskeleton polymerization by activating Arp2/3 complex, thus forming actin-based membrane processes, which are essential for cell migration and cancer cell invasion." (PMID 37049739, 2023). "In addition, we found that biosynthesis of prostaglandins (PGs) and thromboxanes (TXs), synthesis of phosphatidylethanolamine (PE), activation of RAC1, diseases associated with O-glycosylation of proteins, and NOTCH1 signaling in cancer were among the significant pathways." (PMID 35629968, 2022).
cancer (continued). "Since RAC1 has been shown to play a major role in cytoskeleton assembly, tumorigenesis and tumor proliferation, we thus hypothesized that DOCK1 deficiency sensitizes cancer cells to metformin via inhibition of RAC1 activation." (PMID 35217990, 2022). "Furthermore, activated Src was shown to modulate Rac1 and RhoA signaling in migrating cancer cells." (PMID 35563773, 2022). "Similarly, Rac1 also affects the sensitivity of cancer to radiotherapy." (PMID 34079763, 2021). "Hence, PAKs/Rac1-Cdc42-hTERT signaling pathway may play a central role in cancer recurrence and aggressiveness." (PMID 33510789, 2021). "Target genes of miR-576 (CUL3 and RAC1) have been identified to be involved in the regulation of multiple cancer-related biological pathways, and the target genes of miR-616 (ASB13 and FBXW2) have been reported to be associated with the development of other cancers." (PMID 35008363, 2021). "In addition, the good prospects of Rac1 inhibitors in cancer prevention and treatment are exciting." (PMID 34079763, 2021). "Therefore, Rac1 is considered as a potential target for the prevention and treatment of cancer." (PMID 34079763, 2021). "The inactive state of Rac1 can combine with various effector proteins and regulate cell events, such as cell cycle, cell proliferation, apoptosis, stem cell characteristics of cancer cells, and neovascularization, thus participating in the occurrence and development of cancer." (PMID 34079763, 2021). "Therefore, Rac1 is considered a potential target for the prevention and treatment of cancers." (PMID 34079763, 2021). "Thus, low levels of RhoH resulting from aSHM might directly or indirectly promote Rac1-, RhoA- or Cdc42-induced cell division and migration, leading to an increase in cancer progression." (PMID 33923951, 2021). "We show that although Rac1 deletion throughout the intestinal epithelium causes defects in intestinal homeostasis, loss of VAV2, VAV3 and TIAM1 is sufficient to strongly suppress cancer phenotypes and tumourigenesis induced by APC loss, whilst leaving the normal intestinal epithelium unperturbed." (PMID 33397922, 2021). "Moreover, due to the significance of RAC1 in tumour metastasis, therapeutic inhibition of RAC1 may be of significant clinical importance in cancer treatment." (PMID 34215717, 2021). "Interestingly, overexpression of RAC1 was seen in carcinoma-mixed type." (PMID 34679042, 2021). "It is therefore tempting to speculate that only after the levels of RAC1B or the RAC1B:RAC1 ratios in the cancer cells have dropped to a certain threshold are TGFβ’s oncogenic activities freed from inhibition to allow the further development and metastatic progression of human carcinomas." (PMID 33266416, 2020). "Importantly, RAC1 upregulation activates downstream NF-κB under cellular stress and is believed to be a notable way in which RAC1 serves its anti-apoptotic function in cancer cells." (PMID 32545340, 2020). "Therefore, it is tempting to hypothesize that ZNF750 sensitizes cancer cells to chemotherapy by repressing the expression of RAC1." (PMID 33298895, 2020). "In this review, we focus on the role of RAC1 and its cell signaling networks in the promotion of five main tumorigenic phenotypes: anti-apoptotic, pro-proliferative, metastasis-associated/epithelial-to-mesenchymal transition (EMT), cancer stem cell (CSC), and pro-angiogenic." (PMID 32545340, 2020). "Thus, opposite to the tumor-suppressive roles of DGKγ DGKζ may also promote tumorigenesis by potentiating cell invasion and migration in several cancer types by regulating Rac1 and RhoA activity." (PMID 32722576, 2020). "Conceptually, aberrant expression of a Rac-GEF in cancer cells could redirect receptor-mediated signaling toward strengthening Rac1 activation and cell motility, as established for example for the ErbB-receptor activated Rac-GEF P-Rex1 in luminal breast cancer." (PMID 32158759, 2020).